TLR2 (toll like receptor 2)
Diseases named in the same sentence as TLR2 in open-access papers (continued):
Sharing a sentence is not in itself a finding about the gene and the disease.
enteritis (5 papers, 2014 to 2026). Inflammation of the small intestine. "This indicates that TLR4 signaling underlies the majority of the enteritis seen in this model, whereas TLR2 signaling had a protective role, acting to promote mucosal integrity." (PMID 25033044, 2014). "Bulk RNA sequencing of PUFA-exposed model IECs suggested that ATG16L1 is required for TLR2-mediated stress signaling and enteritis, which we corroborated in reporter cells and mice." (PMID 41382985, 2026). "TLR2 may induce enteritis by mediating IRE1α activation and chemokine production." (PMID 37287987, 2023).
H. pylori (5 papers, 2010 to 2022). "Studies show that the cytokine response to Helicobacter infections is mediated by Toll-like receptor 2 (TLR2)." (PMID 32063899, 2019).
head and neck cancer (5 papers, 2019 to 2025). A primary or metastatic malignant neoplasm affecting the head and neck. "TLR2 is also a functional receptor that plays a direct protumorigenic role in head and neck cancers." (PMID 37612282, 2023). "TLR2 agonists (Pam3CSK4 and LTA) modestly increased PD-L1 only in the high-TLR2 line, MDA-MB-231, and this effect was amplified by IFN-γ, consistent with prior findings in head and neck cancer." (PMID 41008792, 2025). "Here, we demonstrated that TLR2 could inhibit apoptosis in HPSCC, which is one of most lethal subgroups of head and neck cancer." (PMID 37612282, 2023).
Hypercholesterolemia (5 papers, 2012 to 2025). An increased concentration of cholesterol in the blood. "The addition of systemic inflammation to hypercholesterolemia significantly increased mRNA expression of TLR-2 and TLR-4 and exacerbated atherosclerotic lesions within the aorta." (PMID 24901254, 2014). "The aorta exhibited intimal hyperplasia, foam cells, and elevated expression mRNA of TLR-2 and TLR-4 in diet-induced hypercholesterolemia." (PMID 24901254, 2014). "Endothelial cell-specific TLR-2 expression is also upregulated via shear stress and hypercholesterolemia independent of TLR-4 expression." (PMID 24901254, 2014). "Therefore, the TLR-2 expression observed in this study may be related to TLR-4 upregulation and/or hypercholesterolemia." (PMID 24901254, 2014).
immune deficiency (5 papers, 2008 to 2022). "The authors suggest that the reason for immune deficiency in the clinical course of CLL may be decreased expression of TLR2 that is too low to activate co-stimulatory factors." (PMID 30196472, 2019). "PSM supplementation significantly (P < 0.05) upregulated expression levels of immune deficiency (IMD) and Toll-like receptor 2 mRNA in shrimp gill tissues directly or indirectly reflected their activation effect in shrimp innate immune response." (PMID 36860454, 2022). "Although these encouraging results suggest a potential therapeutic role of the TLRs inhibition in IIM, it is well known that the TLR2, TLR4 and MyD88 deficiency implies a severe immunodeficiency." (PMID 32164729, 2020).
Infertility (5 papers, 2009 to 2020). "Hence, the validations of these findings in independent cohorts are needed to firmly establish the role of TLR2 gene polymorphism, organ dysfunctions and infertility as well as clinical severity of FGTB." (PMID 26114934, 2015). "FGTB patients with other confounding factors such as duration of infertility, menstrual problems, macroscopic findings of laparoscopy and diagnostic findings of TB infections by different methods were found to be associated with the TLR2 2258G/A and IFN-γ +874(T/A) gene polymorphisms." (PMID 26114934, 2015). "Despite the important role that the TLR2 and IFN-γ plays in immune defence and reproduction, little is known about gene polymorphism in infertile women with FGTB." (PMID 26114934, 2015). "Presently, we proposed to investigate the risk of common single nucleotide polymorphism (SNP) of TLR2 and IFN-γ genes, for their effect on infertility in women with female genital tuberculosis (FGTB) and healthy women as controls." (PMID 26114934, 2015). "In this context, we proposed to conduct a gene polymorphism analysis of TLR2 (2258G/A) and IFN-γ (+874T/A) genes in 175 infertile women with FGTB and 100 healthy women as controls." (PMID 26114934, 2015). "Present study conducted a gene polymorphism analysis of TLR2 (2258G/A) and IFN-γ (+874T/A) genes, for their effect on infertility in women with FGTB and healthy women as controls." (PMID 26114934, 2015). "Recent data suggests that SNPs of TLR2 and IFN-γ genes play an important role in susceptibility to TB among different populations and subsequently, in the development of infertility." (PMID 26114934, 2015). "The level of expression of TLR2 decreased between Periods 1 and 2 in the infertile animals (P < 0.05)." (PMID 19476661, 2009). "Specifically, we speculate that the infertile women with M. tuberculosis infection may have normal levels of TLR2 expression, which may be sufficient to induce a robust local Th1-type host defense (e.g. IFN-γ production) against the infection." (PMID 26114934, 2015). "The genotype distribution of the TLR2 (2258G/A) gene polymorphism among infertile women with FGTB and HCW without TB." (PMID 26114934, 2015). "The TLR2 gene polymorphism study suggest that risk of developing FGTB among infertile women was not significant with AA (1.015) and GA (1.000) genotypes, respectively." (PMID 26114934, 2015). "But, the defects in the factors other than TLR2 may be responsible in infertility and inducing the latent TB among such patients." (PMID 26114934, 2015). "Hence, we were unlikely to provide evidence for an association between the TLR2 gene polymorphisms and its role in inducing infertility among MTB infected cases and controls without TB." (PMID 26114934, 2015). "Thus, maintaining the defective TLR2-IFN-γ signalling in favour of infections may be due to genetic variation in IFN-γ, leads to susceptibility of TB infections and further induces infertility." (PMID 26114934, 2015). "It is therefore necessary to screen a variety of candidate genes, such as those for cytokines and members of the TLR2-IFN-γ mediated signalling pathway with positive IFN-γ/IL-12 feedback loop, to characterize the genetics of female genital tuberculosis susceptibility among infertile women." (PMID 26114934, 2015). "Therefore, the aim of the present study was to investigate the risk of common SNPs of TLR2 gene, specifically at 2258G/A (Arg753Gln) and in IFN-γ gene, specifically at +874T/A in correlation with the occurrence of infertile women with FGTB and healthy women as controls." (PMID 26114934, 2015). "Thus, it remains unclear whether TLR2-mediated signaling is sufficient for chlamydial induction of hydrosalpinx, the surrogate mark of tubal occlusion and infertility." (PMID 23940777, 2013). "We conclude that TLR2 and BGN contribute to sterile inflammation and infertility in man." (PMID 27849015, 2016).
Infertility (continued). "This is the first report to analyse polymorphism in the TLR2 and IFN-γ gene, seeking an association between MTB infection and susceptibility to develop infertility among women with FGTB and control women without TB in an endemic region in India." (PMID 26114934, 2015). "Moreover, good diagnostic accuracy was observed for plasmacytoid dendritic cell BDCA2+CD123+TLR2+ parameters showing negative correlation with infertility." (PMID 32751735, 2020). "Our report could provide observatory practical information on the South Indian population for studies designed at exploring the putative relevance of TLR2 (Arg753Gln) SNPs not only in FGTB, but also in a range of other infectious and inflammatory diseases among infertile patients." (PMID 26114934, 2015).
lymph node metastases (5 papers, 2020 to 2024). "Moreover, TLR-2 is associated with lymph node metastases and distant metastases; its high expression may also contribute to a worse prognosis." (PMID 39273213, 2024). "Moreover, the researchers found a significant relationship between TLR2 expression and lymph node metastases (p < 0.01) and distant metastases (p < 0.01)." (PMID 36982898, 2023). "Of the 95 lymph node metastases, analyzable samples were available for 70 (TLR1), 72 (TLR2), 77 (TLR4), 58 (TLR5), 76 (TLR6), 72 (TLR7), 76 (TLR8) and 70 (TLR9) cases." (PMID 38709790, 2024). "Among CRC patients with lymph node metastases but no distant metastases (Dukes C), a very strong expression of TLR2 predicted a remarkably better survival compared with those patients with a moderate expression." (PMID 32424768, 2020).
measles (5 papers, 2013 to 2024). A highly contagious viral infection caused by the measles virus. "Monocytes are activated via signaling through surface-bound TLR2 during Varicella–zoster virus, measles, and type 1 and 2 Herpes simplex virus (HSV) infections." (PMID 30791481, 2019). "TLR2 can recognize a wide range of viral PAMPs including the glycoproteins gB and gH/gL from HSV and hemagglutinin from measles." (PMID 30791481, 2019). "Furthermore, in order to further enhance the immunostimulatory potential of oncolytic cell death, we have engineered measles strains to express the Helicobacter pylori neutrophil-activating protein (NAP), a potent TLR2 agonist." (PMID 38216554, 2024).
Opportunistic infection (5 papers, 2012 to 2025). An infection that is caused by a pathogen that would generally not be able to cause an infection in a host with a normal immune system. "By decreasing the expression of TLR2, an important gatekeeper of the skin, the risk of opportunistic infections is increased." (PMID 30319618, 2018). "The interaction of PPRV H protein with TLR2 might induce tolerance to subsequent activation by bacterial components, resulting in high sensitivity to opportunistic infections associated with acute PPRV infection." (PMID 33522421, 2021). "Dendritic cells obtained from HIV-infected individuals co-infected with M. tuberculosis have increased expression of TLR2 and TLR4, which may promote HIV replication and contribute to the faster disease progression observed in patients with opportunistic infections." (PMID 22844428, 2012).
oral squamous cell carcinoma (5 papers, 2011 to 2022). "One of them, TLR2, was found to be at great risk in oral squamous cell carcinoma, as evidenced by the high mRNA expression in 5/6 oral squamous cell carcinoma cell lines." (PMID 34158059, 2021). "The aim of this study was to investigate the expression of toll-like receptor 2 (TLR2) on cells associated with oral squamous cell carcinoma, epithelial dysplasia and irritative hyperplasia, using immunohistochemistry." (PMID 21179035, 2011). "Collectively, these evidences demonstrate that RETNLB deficiency suppresses the viability, mobility and invasiveness of oral squamous cell carcinoma cells partly by inactivating the TLR2/4/ERK signaling pathway." (PMID 34158059, 2021). "Mechanistically, RETNLB possibly affects the phenotypes of oral squamous cell carcinoma cells partly by modulating the TLR2/4/ERK signaling pathway." (PMID 34158059, 2021). "Thus, western blot assay was used to verify our suspicion that RETNLB played the tumor-promoting effect in oral squamous cell carcinoma cells through regulating the TLR2 and TLR4." (PMID 34158059, 2021). "Furthermore, we revealed that RETNLB acted a promoting role in the malignant development of oral squamous cell carcinoma cells via regulating TLR2/4/ERK pathway." (PMID 34158059, 2021). "These detections demonstrated that downregulation of RETNLB suppresses the progression of oral squamous cell carcinoma cells might by inactivation of the TLR2/4/ERK pathway." (PMID 34158059, 2021). "P. gingivalis was previously shown to promote growth of cancer cells (of non-pancreatic origin, i.e., oral squamous cell carcinoma) through a TLR2 dependent mechanism." (PMID 32824786, 2020).
pancolitis (5 papers, 2010 to 2017). Ulcerative colitis that involves the entire colon. "Emerging evidence from genetic and experimental studies associate a TLR2-R753Q polymorphism with severe pancolitis in UC patients and impaired intestinal barrier integrity." (PMID 26067254, 2015). "Polymorphisms in TLR1 and TLR2 genes (TLR1 R80T and TLR2 R753G) have been associated with pancolitis in UC patients." (PMID 21647408, 2011). "Regarding the low-prevalence variant Arg753Gln (rs5743708) in TLR2, a previous case-control association study comprising 285 European IBD patients (of which 106 had UC) described an association of this variant with pancolitis, with a relative risk of 3.3 in heterozygous patients." (PMID 28388655, 2017).
pulpitis (5 papers, 2017 to 2022). Inflammation of the dental pulp. "Additionally, the collaborative relationship of Dectin-1 with TLR-2 in dental pulp inflammation was identified." (PMID 36463168, 2022). "Nonetheless, it was evident that both TLR2 and TLR4 were induced on the macrophages and dendritic-like cells at the early stage of pulpitis." (PMID 30631444, 2018). "Dental pulps with pulpitis suffer higher expressions of proinflammatory cytokines (IL-1α, IL-1β, IL-6, and TNF-α) and innate immune response (TLR2, TLR4) than pulps without pulpitis." (PMID 31695620, 2019). "Furthermore, deciduous pulps with pulpitis suffered higher expressions of proinflammatory cytokines (IL-6 and MCP-1) and innate immune response (TLR1, TLR2, TLR3, TLR6, and TLR8) than pulps without pulpitis." (PMID 28377925, 2017).
retinal degeneration (5 papers, 2018 to 2024). Degeneration of the retina. "We found that increased expression of Tlr2 and its adaptor molecules was associated with the progression of retinal degeneration and the retinal inflammatory response in two genetically unrelated mouse models of RP." (PMID 34360582, 2021). "In previous studies, TLR2 was reported as a mediator of retinal degeneration in response to oxidative stress and was hypothesized to act as a “bridge” between oxidative damage and complement-mediated retinal pathology." (PMID 39062973, 2024). "To examine the potential link between retinal degeneration and the innate immune response, we first analyzed expression of Tlr2 and TLR-adaptor genes in two genetically unrelated RP mouse models, the rd10 (Pde6brd10/rd10) mouse and the P23H/+ (RhoP23H/+) mouse." (PMID 34360582, 2021). "Furthermore, in mouse models of oxidative stress, including CEP-induced retinal degeneration, TLR2 inhibition resulted in decreased complement deposition and activation, and a protection of the RPE and photoreceptors from cell death." (PMID 34445096, 2021). "Interestingly, TLR2 and other PRRs were also found to be inducible in Müller cells early in the course of progressive retinal degeneration, suggesting that Müller cells may become able to respond to stress directly during the course of a more chronic neurodegenerative condition." (PMID 29904087, 2018).
schistosomiasis (5 papers, 2014 to 2024). An infectious disease caused by parasitic trematodes of the genus Schistosoma that colonize human blood vessels and release eggs that can cause granulomatous reactions leading to acute (swimmer's itch or acute schistosomiasis syndrome) or chronic disease. "In this study, we identified a novel role for macrophages in liver pathogenesis using a S. japonicum-infected mouse model and present TLR2 signaling as a novel potential therapeutic target for schistosomiasis." (PMID 30589840, 2018). "Additionally, we showed that this mechanism is also responsible for the immunoregulatory activity in schistosomiasis, which provides an early in vitro demonstration of the role of ES Ags in modulating immunopathology downstream of TLR2." (PMID 30589840, 2018). "For this reason, the results generated from this study might provide evidence supporting the necessity to include TLR2 signaling as a novel therapeutic target for schistosomiasis." (PMID 30589840, 2018). "Therefore, we investigated the effectiveness of both MSC and the TLR2/4-ligated MSC to regulate Th1/Th2 response in the schistosomiasis model, which will provide new information about the potential of MSC-based therapies in the treatment of Schistosoma egg-induced liver pathology." (PMID 32503644, 2020). "We could show, that systemic IFN-γ responses were absent in TLR2,4-double-deficient mice with schistosomiasis." (PMID 25398130, 2014). "So, we questioned whether TLR2/TLR4-ligated MSC could also modulate Th1/Th2 responses and thus have different roles in the schistosomiasis model." (PMID 32503644, 2020).
tuberculous meningitis (5 papers, 2008 to 2021). "The association between TLR2 T597C and the Beijing strains was strongest for patients with meningeal TB (control vs. TBM East-Asian Beijing OR = 4.48 [95% C.I. 2.00–10.04], P<0.001)." (PMID 18369480, 2008).
tularemia (5 papers, 2012 to 2023). Tularemia is an infection caused by the bacterium Francisella tularensis. "Also, a separate study demonstrated that TRAM−/− mice exhibited a greater susceptibility to TLR2-driven Francisella tularensis infection when compared to WT mice indicating a possible, yet to be dissected, role for TRAM in TLR2 signaling." (PMID 25211222, 2014). "Comparison of WT and ∆tolC LVS in the mouse pneumonic tularemia model revealed distinct roles for TLR2 and MYD88 in early responses to infection and host survival." (PMID 37404047, 2023). "Experiments using the mouse pneumonic tularemia model confirmed the in vivo relevance of these findings, revealing contributions of TLR2 and MYD88 signaling to the protective host response to F. tularensis, which is modulated by the bacteria to promote virulence." (PMID 37404047, 2023). "Finally, experiments using the mouse pneumonic tularemia model revealed that both TLR2 and MYD88 signaling contribute to the early host response to LVS infection in vivo and to the protection against lethal infection." (PMID 37404047, 2023). "A growing body of data implicates miR-146 and miR-155 in macrophage tolerance to TLR2 agonists as well as LPS, and it will therefore be of interest in future studies to determine if miR-150, miR-146, and miR-155 synergize to inhibit macrophage activation capacity during tularemia." (PMID 25295729, 2014). "Given our findings that F. tularensis targets TLR2- and MYD88-dependent signaling during macrophage infection, we next sought to determine the impact of this bacteria-host interplay in the mouse pneumonic tularemia model." (PMID 37404047, 2023). "Despite similar requirements for TLR2 and MYD88 in controlling intracellular replication of Francisella in macrophages, we found that MYD88 plays a more significant role in protection than TLR2 in the mouse pneumonic tularemia model." (PMID 37404047, 2023). "In a C57BL/6 mouse model of respiratory tularemia initiated by infection with Ft LVS, the absence of TLR2 engenders accelerated and greater mortality, higher bacterial burden, and dysregulated cytokine production." (PMID 23554897, 2013).